CDC20 (cell division cycle 20)
Diseases named in the same sentence as CDC20 in open-access papers (continued):
Sharing a sentence is not in itself a finding about the gene and the disease.
glioma (continued). "Finally, we conducted a clinical analysis using the CGGA and TCGA datasets and our samples and discovered that CDC20 was overexpressed in high-grade gliomas versus low-grade gliomas and normal brain tissue." (PMID 40092489, 2025). "Additionally, our rescue experiments showed that restoration of CDC20 expression reversed the inhibitory effect of HMGN2 knockdown on glioma proliferation and reduced the proportion of cells in the G2/M phase." (PMID 40092489, 2025). "HMGN2 and CDC20 expression levels are positively correlated in glioma tissues." (PMID 40092489, 2025). "Moreover, we found that CDC20 expression was negatively correlated with the survival time of patients with glioma." (PMID 40092489, 2025). "In summary, these results indicated that HMGN2 and CDC20 are crucial for glioma progression and may serve as potential biomarkers for predicting the prognosis of patients with glioma." (PMID 40092489, 2025). "Finally, we identified HMGN2 and CDC20 as potential biomarkers and therapeutic targets for the treatment of glioma." (PMID 40092489, 2025). "Hence, these results suggest that CDC20+KIF20A+PTTG1+ glioma cell subpopulation is potential target in effective TMZ‐sensitizing therapies." (PMID 40047299, 2025). "Furthermore, CDC20 was restrictively activated in the hypoxic area labeled by hypoxyprobe in the long‐term (4 weeks) glioma intracranial mouse model." (PMID 40047299, 2025). "Therefore, the CDC20+KIF20A+PTTG1+ cell subpopulation featured aberrant oncogenic molecular activity in glioma, suggesting that these cells are therapeutically vulnerable to glioma progression." (PMID 40047299, 2025). "Moreover, canonical oncogenic proliferation markers MKI67 and TOP2A were upregulated in the CDC20+KIF20A+PTTG1+ cell subpopulation of glioma samples." (PMID 40047299, 2025). "CDC20 has an oncogenic function in tumourigenesis, and its expression has been reported to be inhibited in vitro by curcumin and rottlerin, resulting in reduced survival of pancreatic cancer cells and glioma cells." (PMID 37755981, 2023). "In addition, IHC images of the collected glioma samples also demonstrated that CDC20 were increased with the rise of WHO grades in glioma, and higher than NBT." (PMID 36792756, 2023). "Besides, we found that CDC20 gene, one of the recently identified markers of genomic instability in glioma, was significantly upregulated in the GU cluster (p < 0.001, Mann–Whitney U test)." (PMID 35069679, 2021). "EPIC1 exhibits its functions through targeting Cdc20 in glioma cells." (PMID 32322669, 2020). "Consistently, overexpression of EPIC1 increased the Cdc20 expression in three glioma cell lines." (PMID 32322669, 2020). "Upregulation of Cdc20 abrogated EPIC1 siRNA-induced apoptosis in three glioma cell lines." (PMID 32322669, 2020). "We observed that downregulation of Cdc20 inhibited cell viability in three glioma cell lines." (PMID 32322669, 2020). "Moreover, our data suggest that EPIC1 exerts its biological functions via targeting Cdc20 in glioma cells." (PMID 32322669, 2020). "We found that overexpression of Cdc20 increased cell viability in three glioma cell lines." (PMID 32322669, 2020). "Recently, rottlerin was found to downregulate the expression of Cdc20 in glioma cells." (PMID 28165402, 2017). "Our invasion assay showed that depletion of Cdc20 suppressed glioma cell invasion." (PMID 27626499, 2016). "We found that overexpression of Cdc20 promoted cell growth in both glioma cells." (PMID 27626499, 2016). "Overexpression of Cdc20 reversed the cell migration inhibition in rottlerin-treated glioma cells." (PMID 27626499, 2016). "In the current study, we investigated whether Cdc20 plays an important role in regulation of cell growth, apoptosis, cell cycle, migration and invasion in glioma cells." (PMID 27626499, 2016). "In addition, compound 331 was found to be a potential drug selectively targeting glioma cells through down-regulation of Cdc20." (PMID 27626499, 2016).
glioma (continued). "Importantly, we also found that p21, one of Cdc20 targets, was increased in both glioma cells after rottlerin treatment." (PMID 27626499, 2016). "Similarly, Cdc20 cDNA transfection reversed the upregulation of p21 by rottlerin in both glioma cells." (PMID 27626499, 2016). "Moreover, Cdc20 overexpression abrogated inhibition of cell invasion induced by rottlerin in glioma cells." (PMID 27626499, 2016). "Our findings indicted that rottlerin could exert its tumor suppressive function by inhibiting Cdc20 pathway which is constitutively active in glioma cells." (PMID 27626499, 2016). "We found that down-regulation of Cdc20 inhibited cell growth in both glioma cells." (PMID 27626499, 2016). "We also observed that down-regulation of Cdc20 triggered cell apoptosis in glioma cells." (PMID 27626499, 2016). "We provided definitive evidence that c-Myc and Cdc20 alone are insufficient to induce glioma." (PMID 26993778, 2016). "We observed that rottlerin significantly inhibited the expression of Cdc20 in glioma cells, implying that Cdc20 could be a novel target of rottlerin." (PMID 27626499, 2016). "We also demonstrated that rottlerin could down-regulate the expression of Cdc20, leading to anti-tumor activity in glioma cells." (PMID 27626499, 2016). "Additionally, Cdc20 overexpression abrogated the inhibition of Cdc20 in glioma cells treated with rottlerin." (PMID 27626499, 2016). "Our scratch assay showed that over-expression of Cdc20 promoted the glioma cell migration." (PMID 27626499, 2016). "Consistently, p21 expression is downregulated in Cdc20-transfected glioma cells." (PMID 27626499, 2016). "Consistently, Cdc20 shRNA promoted rottlerin-induced p21 level in both glioma cells." (PMID 27626499, 2016). "Moreover, our Western blotting analysis revealed that rottlerin significantly decreased Cdc20 protein levels in glioma cells." (PMID 27626499, 2016). "As TICs are highly enriched in high-grade gliomas, CDC20 may play an important role in the maintenance of TICs." (PMID 25938542, 2015). "Overexpression of CDC20 could significantly increase cell viability of glioma cells treated with compound 331 (20 μM, 48 h)." (PMID 26153143, 2015). "CDC20 overexpression could further rescue the increase of multi-nuclei cells and G2/M arrest in compound 331 treated glioma cells." (PMID 26153143, 2015). "Moreover, we collected glioma tissues for immunohistochemistry assay to detect CDC20 expression." (PMID 40092489, 2025). "Overexpression of EPIC1 via targeting Cdc20 could be useful in glioma treatment." (PMID 34178658, 2021). "Moreover, Cdc20 overexpression inhibited apoptosis of glioma cells." (PMID 32322669, 2020). "Furthermore, overexpression of Cdc20 enhanced cell invasion in glioma cells." (PMID 32322669, 2020). "Thus, inhibition of EPIC1 or Cdc20 could be a potential strategy for overcoming the resistance to TMZ in glioma patients." (PMID 32322669, 2020). "Moreover, depletion of Cdc20 abolished EPIC1-mediated TMZ resistance in glioma cells." (PMID 32322669, 2020). "Moreover, depletion of Cdc20 enhanced cell growth inhibition induced by rottlerin in glioma cells." (PMID 27626499, 2016). "Our findings demonstrated that rottlerin could be a potential inhibitor of Cdc20 in glioma cells." (PMID 27626499, 2016). "Furthermore, Cdc20 level was significantly correlated with glioma grade and survival time." (PMID 27626499, 2016). "Therefore, we explored whether rottlerin could down-regulate the expression of Cdc20 in glioma cells." (PMID 27626499, 2016). "Importantly, we found that Cdc20 cDNA transfection upregulated Cdc20 expression in glioma cells." (PMID 27626499, 2016). "Furthermore, we determined whether rottlerin exerts its anticancer function via inactivation of Cdc20 in glioma cells." (PMID 27626499, 2016). "Notably, Cdc20 shRNA enhanced cell invasion inhibition in rottlerin-treated glioma cells." (PMID 27626499, 2016).
glioma (continued). "Therefore, down-regulation of Cdc20 by rottlerin could be a promising therapeutic strategy for the treatment of glioma." (PMID 27626499, 2016). "Here, we identified that rottlerin could be a new Cdc20 inhibitor in glioma cells." (PMID 27626499, 2016). "Furthermore, Cdc20 shRNA promoted inhibition of migration induced by rottlerin in glioma cells." (PMID 27626499, 2016). "Similarly, CDC20 overexpression decreased the percentage of annexin V-positive and PI-negative cells and the enzymatic activities of caspase-3/7 in glioma cells treated with compound 331 (20 μM, 48 h)." (PMID 26153143, 2015). "In addition, overexpression of CDC20 could also significantly rescue the glioma cells ability to form colonies." (PMID 26153143, 2015). "CDC20, KIF20A and PTTG1 remained co‐expressed in glioma cells, and this cell subpopulation was increased in four recurrence glioma cases under therapy." (PMID 40047299, 2025). "This subgroup is naturally present at high grades and shows more CDC20+KIF20A+PTTG1+ cells than LGG, suggesting a critical role in glioma progression." (PMID 40047299, 2025). "The CDC20 expression plot from GEPIA and CGGA showed that CDC20 expression was up-regulated in GBM compared with that in low-grade gliomas." (PMID 40092489, 2025). "In our study, the PRMT6-CDC20-CDKN1B axis regulates glioma cell cycle progression is identified, therefore PRMT6 and CDC20 functionally play critical roles in GBM." (PMID 36792756, 2023). "Bioinformatics analysis of TCGA and CGGA datasets results showed that CDC20 was overexpressed in glioma, especially in GBM, and the increasing of CDC20 in glioma patients correlated with poorer prognosis." (PMID 36792756, 2023). "Univariate analysis and multivariate analysis of the correlation of the expression of CDC20, UBE2C, WDR62, DTL, HOXB4 and TRIM38 with OS among glioma patients." (PMID 33914773, 2021). "Next, to further investigate the role of Cdc20 in EPIC1-mediated tumor progression, we overexpressed Cdc20 in glioma cells after EPIC1 siRNA transfection." (PMID 32322669, 2020). "Here, we found that EPIC1 downregulation inhibited the expression of Cdc20, while overexpression of EPIC1 elevated Cdc20 expression level in glioma." (PMID 32322669, 2020). "Overexpression of cell division cycle 20 (CDC20) in glioma enhanced tumor TMZ resistance and reduced OS of glioma patients." (PMID 32642801, 2020). "Subsequently, we evaluated the prognostic accuracy of CCNB2, CDC20 and MYBL2 by calculating the time‐dependent ROC, AUC (area under the ROC curve) for one‐, three‐ and five‐year survival in glioma patients." (PMID 32696617, 2020). "The glioma cells were infected with lentiviruses containing the full length of EPIC1 and transfected with Cdc20 siRNA." (PMID 32322669, 2020). "Moreover, we explored whether rottlerin could inhibit the expression of Cdc20 in glioma cells." (PMID 27626499, 2016). "Therefore, rottlerin could be a potential efficient agent to inhibit Cdc20 in glioma." (PMID 27626499, 2016). "We previously reported that some GBM signature genes, including c-Myc and Cdc20, distinguish GBM from other low-grade gliomas." (PMID 26993778, 2016). "Expression of six SAC genes, BUB1, BUB1B, CDC20, CENPE, MAD1L1 and TTK were found to be significantly positively correlated with WHO grades of glioma patients (p<0.01)." (PMID 22022424, 2011). "In pairwise comparisons of glioma samples, two genes (BUB1B, CDC20) showed significant difference between grade II and grade IV (p<0.05), while expression in grade III does not significantly differ from grade II or grade IV for most genes." (PMID 22022424, 2011). "Nevertheless, antibody stains for proteinsBUB1, BUB1B, BUB3, CDC20, and TTK were at significantly higher levels in high grade glioma than in normal brain by this test." (PMID 22022424, 2011).
glioma (continued). "RNA levels of eight major mitotic spindle assembly checkpoint (SAC) genes (BUB1, BUB1B, BUB3, CENPE, MAD1L1, MAD2L1, CDC20, TTK) significantly correlated with glioma grade and six also significantly correlated with survival time." (PMID 22022424, 2011). "CDC20, KIF20A and PTTG1 were specifically co‐expressed in Bio‐C8 LGG glioma cells." (PMID 40047299, 2025). "Finally, we combined CDC20 and KIF20A related inhibitors Apcin and Paprotrain to performed therapy experiments in glioma PDOs." (PMID 40047299, 2025). "Impressively, CDC20, KIF20A and PTTG1 were naturally and highly co‐expressed in GBM glioma cells." (PMID 40047299, 2025). "In summary, our results show that HMGN2 is involved in the transcriptional regulation of CDC20 by modulating the acetylation level of H3K27 in the CDC20 promoter region, thereby affecting the cell cycle distribution and proliferative ability of gliomas." (PMID 40092489, 2025). "Then, a series of phenotypic assays were performed to investigate whether CDC20, KIF20A and PTTG1 knockdown inhibits proliferation phenotypes in glioma cell lines." (PMID 40047299, 2025). "Moreover, analysis of genes and proteins that interact with KIF18A showed that several molecules related to cell cycle and cell division, such as RRP7A, ANAPC4, WEE1, CDC20, and NDC80, were enriched in glioma." (PMID 35591854, 2022). "Interfering with CDC20 expression can inhibit the growth and invasion of osteosarcoma cells, but the effect on glioma cells has not been well studied." (PMID 34753395, 2021). "Moreover, Cdc20 inhibition retarded cell invasion and abolished EPIC1-mediated enhancement of cell invasive activity in glioma cells." (PMID 32322669, 2020). "MIIP is able to interact with Cdc20 and suppress the activity of APC/CCdc20, thus blocking the degradation of two mitotic check proteins, cyclin B1 and securing, leading to impaired mitotic transition in glioma and colon cancer model." (PMID 31092266, 2019). "Then, because single c-Myc and Cdc20 genes are not sufficient to induce glioma in both CDKN2A+/+ and CDKN2A−/− Ntv-a mice, we explored the role of c-Myc and Cdc20 in glioma development in a RCAS/Ntv-a mouse model using the combination of kRas and Akt3." (PMID 26993778, 2016). "Compound 331 selectively upregulated miR-494 and downregulated CDC20 in glioma cells but not in astrocytes." (PMID 26153143, 2015). "This highlights the possibly useful role of CDC20 and BUB1B in estimating grades of glioma samples." (PMID 22022424, 2011). "Interestingly, Ki-67 RNA level was outperformed by BUB1B and CDC20, overall, and by BUB1 and TTK when applied to grade II gliomas." (PMID 22022424, 2011). "Due to non-toxic nature, inactivation of Cdc20 by rottlerin could be a safer strategy for the treatment of glioma." (PMID 27626499, 2016). "Compound 331 upregulated miR-494 and downregulated CDC20 in glioma cells but not in astrocytes." (PMID 26153143, 2015).
pancreatic cancer (35 papers, 2012 to 2025). "High expression of CDC20 showed an association with tumor recurrence and patient death in bladder cancer and pancreatic cancer." (PMID 33922264, 2021). "Consistently, high Cdc20 expression is associated with poor prognosis in oral squamous cell carcinoma, gastric cancer, urothelial bladder cancer, colorectal cancer, non-small cell lung cancer, and pancreatic cancer." (PMID 28165402, 2017). "As a key regulatory protein in the cell cycle, in recent years, CDC20 has been proven to promote the proliferation, migration, and invasion of pancreatic cancer." (PMID 36900292, 2023). "Aberrant expression of CDC20 is confirmed to be related to malignant progression of various cancers, and down-regulation of CDC20 suppresses the migration of pancreatic cancer cells." (PMID 35212610, 2022). "Cell division cycle 20 (Cdc20) plays an important oncogenic role in the growth of pancreatic cancer and higher expression of Cdc20 is closely related to a poor prognosis." (PMID 34572272, 2021). "In pancreatic cancer, CDC20 can promote tumor cell proliferation and affect the progression of pancreatic cancer." (PMID 34917126, 2021). "Curcumin was shown to inhibit CDC20 expression in pancreatic cancer cells, and the discovery of specific CDC20 inhibitors for cancer treatment would be beneficial." (PMID 34753395, 2021). "Overexpression of CDC20 in tumor tissues was related with poor differentiation and a lower 5-year recurrence-free survival rate of pancreatic cancer patients, and a short survival of colorectal cancer." (PMID 33777535, 2021). "In one study, overexpression of CDC20 enhanced cell proliferation and invasion, while down-regulation of CDC20 promoted anti-tumor activity in pancreatic cancer cells." (PMID 30765611, 2019). "In line with this, overexpression of SPRY4-IT1 increased Cdc20 expression in pancreatic cancer cells." (PMID 29489909, 2018). "Our findings indicated that SPRY4-IT1 exerts its function in part through regulation of Cdc20 in pancreatic cancer." (PMID 29489909, 2018). "To reveal the potential molecular mechanism of SPRY4-IT1 in pancreatic cancer cells, we measured the expression of Cdc20 (cell division cycle 20) using Western blotting analysis." (PMID 29489909, 2018). "Mechanistically, suppression of SPRY4-IT1 inhibited the expression of Cdc20 in pancreatic cancer cells." (PMID 29489909, 2018). "High CDC20 expression has been reported in various malignancies and many tumor cells, including pancreatic cancer cells." (PMID 22475564, 2012). "CDC20 mRNA expression was significantly higher in pancreatic cancer tissues (by 21.98-fold) and all exponentially growing cell lines (by 57.68-fold) than in normal pancreas and pancreatitis tissue." (PMID 22475564, 2012). "Additionally, curcumin has been reported to inhibit the expression of CDC20 in pancreatic cancer cells." (PMID 40439120, 2025). "Furthermore, overexpression of CDC20 enhances proliferation and invasion of pancreatic cancer cells." (PMID 39114311, 2024). "Also, the depletion of CDC20 in pancreatic cancer patients suppressed cell growth, induced G2/M cell cycle arrest, boosted the cytotoxic effect of paclitaxel treatment, and enhanced the effect of gamma-irradiation." (PMID 39061186, 2024). "In addition, silencing CDC20 in pancreatic carcinoma cells with siRNA inhibited cell proliferation and triggered G2/M phase arrest." (PMID 39795587, 2024). "Inhibits Cdc20 expression in drug resistant pancreatic cancer cells." (PMID 37682144, 2023). "In addition, the downregulation of CDC20 was reported to increase the activity of the curcumin-mediated anti-tumor treatment against pancreatic cancer." (PMID 35622386, 2022). "In the current study, we identified that SPRY4-IT1 could upregulate the expression of Cdc20 oncoprotein in pancreatic cancer." (PMID 29489909, 2018).